CTLA4 (cytotoxic T-lymphocyte associated protein 4)
Diseases named in the same sentence as CTLA4 in open-access papers (continued):
Sharing a sentence is not in itself a finding about the gene and the disease.
COVID-19 (continued). "This is supported by our findings showing that MAIT cells in COVID-19 patients express high levels of activation and exhaustion markers, and that expression of HLA-DR and CTLA-4 negatively correlates with MAIT cell frequency in COVID-19 patients." (PMID 33546489, 2021). "In contrast, the percentages of several CD4+ T cell subsets, including CD4-Naive, CD4-LTB, CD4-ICOS, Treg-CTLA4, as well as cycling T cells, were significantly increased in severe COVID-19 than those in mild COVID-19." (PMID 33101705, 2020). "Apart from severe lymphopenia, CD4+ and CD8+ T cells from patients with severe COVID-19 exhibited increased expression of CTLA-4 and PD-1 and a high expression of Ki67 as a marker for recent proliferation." (PMID 32937615, 2020). "Furthermore, in COVID-19 patients, there is an observed upregulation in the expression of immune checkpoint molecules such as PD-1, CTLA-4, TIM-3, LAG-3, TIGIT, and VISTA." (PMID 39967737, 2025). "In addition, the SP group had a high suppressive score of all Tregs, CCR7+ Tregs, CD69+ Tregs, and CTLA4+ Tregs in severe COVID-19 patients." (PMID 40114921, 2025). "In addition, an increase in central memory Tregs with elevated expression of CTLA-4 and IL-10 was observed in patients with mild, moderate, and severe COVID-19." (PMID 39519310, 2024). "The safety of opaganib has been established in clinical trials with adults with advanced cancer or severe COVID-19, and so opaganib has excellent potential for treating patients with NB, particularly in combination with temozolomide and irinotecan or anti-CTLA-4 antibody." (PMID 38730731, 2024). "However, the frequency of NKG2A+/PD-1+/CTLA-4+/TIGIT+ exhaustion CTL in dead patients or patients with severe COVID-19 is significantly higher than in moderate/mild patients, suggesting that it is associated with patients’ poor prognosis." (PMID 36960050, 2023). "Furthermore, CTLA-4, which is an important functional marker of Tregs, has been studied to manage COVID-19." (PMID 36992283, 2023). "Levels of PD-1 and CTLA-4 expressed on both CD4+T and CD8+T were observed to be upregulated in COVID-19 patients, which may reflect an association with the severity of COVID-19." (PMID 37391394, 2023). "Despite these limits, they have generally shown that the COVID-19 vaccine is immunogenic in most patients with ARD, and different factors associated with a blunted vaccine response have been identified, such as anti-CD20 or CTLA4-Ig therapy." (PMID 38006015, 2023). "However, severe COVID-19 patients had more CTLA-4+ CD62L+ cells (p=0.01) and PD-1+ CD62L+ cells (p=0.049) in the total CD4+ population compared to non-severe patients." (PMID 36817450, 2023). "Our observation prompts additional trials aimed at confirming whether CTLA4-Ig is contraindicated in the treatment of RMD patients with COVID-19, being detrimental to the elicitation of the immune response to vaccination." (PMID 35757699, 2022). "Thus CD4 + and CD8 + T cells in severe COVID-19 patients presented with concomitant over-expressions of co-inhibitory molecules PD-1, PD-L1, CTLA-4 and TIM-3 in accordance with the development of a state of T exhaustion after severe SARS-Co-V2 infection." (PMID 35246776, 2022). "Based on these studies, there are some evidence supporting the use of a panel of IC receptors/ligands as prognostic biomarkers in severe COVID-19 patients; this panel could include upregulations of PD-1, CTLA-4, TIM-3, PD-L1, Gal-3, and Gal-9." (PMID 35432324, 2022). "Finally, increased expression of the co-inhibitory receptors PD-1, CTLA-4 or TIM-3 have been reported and associated with disease severity in COVID-19 patients." (PMID 35246776, 2022). "Moreover, a specific upregulation of CTLA-4 was seen in BALF CD8+ T cells isolated from severe COVID-19 patients." (PMID 35432324, 2022).
COVID-19 (continued). "In light of this immune response, immunotherapy administration might be conducive to patients with COVID-19 because it activates exhausted T cells by blocking PD-1/PD-L1 or CTLA-4." (PMID 35271463, 2022). "However, our study provides information on the behavior of sCD40 and CTLA-4 in subjects with comorbidities who recovered from mild COVID-19." (PMID 36297185, 2022). "Other studies demonstrated that the presence of CTLA-4 and PD-1 on T cells may modulate the immune response and protect the vital organ from an excessive inflammatory environment in severe COVID-19 patients." (PMID 35432324, 2022). "This provided the basis for using CTLA-4-based therapy in COVID-19 patients." (PMID 35874688, 2022). "Besides CTLA4, an increase in activated CXCR4 + T cells homing to the lungs is associated with fatal COVID-19." (PMID 36510222, 2022). "Notably, the percentage of Treg-CTLA4 cells increased significantly in most COVID-19 groups over controls, but the proportions of other CD4+ T cell subsets did not change significantly." (PMID 35095917, 2021). "Finally, as an indicator of CD8+ T cell exhaustion, both PD-1 and TIM-3, CTLA-4, and LAG-3 may be associated with the disease severity of COVID-19." (PMID 36045684, 2022). "In our study, severely ill COVID-19 patients had greater frequencies of CD4+ T cells co-expressing CD62L and immune checkpoint markers, specifically PD-1 and CTLA-4." (PMID 36817450, 2023). "We also observed higher expression of T cell exhaustion markers, i.e., TIM-3, LAG3, CD152 or CTLA4 and CD279 or PD-1 in the recovered individuals compared to the active COVID-19 and healthy individuals." (PMID 36532041, 2022). "A high level of exhaustion markers has been reported in the severe COVID-19 patients, however, we observed elevated expression of the T cell exhaustion markers like LAG3, CTLA4, and PD-1 in the recovered individuals." (PMID 36532041, 2022). "We next evaluated the expressions of the exhaustion markers PD-1, PD-L1, CTLA-4 and TIM-3 on CD4 + and CD8 + T cells in COVID-19 patients sampled at D0 and D20 compared to HV." (PMID 35246776, 2022). "An exhausted CD8+ T-cell phenotype with an upregulation of IRs, such as PD-1, TIM-3, LAG-3, CTLA-4, NKG2A, and CD39, has been described in patients with COVID-19, particularly in those with severe disease." (PMID 34413488, 2021). "MAIT cells from COVID-19 patients expressed significantly higher levels of the activation markers CD38, CD69 and HLA-DR, as well as of the exhaustion markers CTLA-4 and PD-1, compared to healthy controls." (PMID 33546489, 2021). "In the acute phase of severe COVID-19, a considerable proportion of SARS-CoV-2-specific CD8+ T cells express TIM-3, LAG-3, TIGIT, and CTLA-4." (PMID 34413488, 2021). "They reported that most patients with CTLA-4 insufficiency and COVID-19 had nonsevere disease and lacked autoantibodies against type 1 Interferons." (PMID 40963607, 2025). "Prior findings reported that, in COVID-19, especially in severe patients, activation and exhaustion markers on the T cell surface were upregulated during acute infection, such as CD69, OX40, CD38, 4-1BB, PD-1, CTLA-4, LAG-3, TIM-3, and TIGIT." (PMID 39355257, 2024). "Level of CTLA-4 among sera of participants groups with or without COVID-19 according to type of vaccine." (PMID 38180994, 2024). "Namely, we found an enrichment of two COVID-19-unique inhibitory interactions between APCs and CD8+ T cells, CTLA4/CD86 and HAVCR2/LGALS9, which may be out of necessity to curb the heightened inflammation present in severe COVID-19." (PMID 36992700, 2023). "Interestingly, we detected a small population of exhausted CD8+ T cells (TEX) characterized by expression of TIGIT, CTLA4, CD279 (PD-1) and HAVCR2 (Tim-3) that was exclusive to the severe COVID-19 group, a finding which has been reported by others before." (PMID 36591270, 2022).
COVID-19 (continued). "The expression of immunological checkpoint inhibitor CTLA4 is enhanced on the surface of T-cells due to induction of INF-γ production by neutrophils and monocytes, which are abundant in the peripheral blood of people with COVID-19." (PMID 36510222, 2022). "We also evaluated CTLA-4, an important co-inhibitory molecule produced by Tregs, in the serum of non-comorbid and comorbid patients who recovered from mild COVID-19." (PMID 36297185, 2022). "Furthermore, the inhibitory membrane receptors expressed by CD8+ T cells, such as PDCD1 (PD1), CTLA4, and HAVCR2 (TIM3), were significantly upregulated in severe COVID-19 patients when compared with those in healthy people and mild COVID-19 patients." (PMID 34305939, 2021). "Amongst T-cell and monocytes/macrophages, some immune-stimulatory or auto-regulatory interactions were seen (CTLA4 or CD28/CD80 or CD86, CCL5/CCR5), but specific epithelial to T-cell interactions in critical COVID-19 were limited to pro-inflammatory ICAM1-mediated interactions." (PMID 33473155, 2021). "Emerging evidence demonstrated that COVID-19 vaccination in the ipsilateral arm was immunogenically superior to the contralateral arm vaccination in the neutralizing activity of anti-S IgG, median spike-specific CD8 T-cell levels, and CTLA-4 expression on spike-specific CD4 T-cells." (PMID 38250886, 2024). "Level of CTLA-4 among sera of participants groups with or without COVID-19 according to age groups." (PMID 38180994, 2024). "Along with hyperinflammation in severe COVID-19, there is overwhelming evidence in the literature pointing towards cytotoxic cell immunosuppression due to upregulation of immune exhaustion markers (PD-1, TIGIT, Tim-3, CTLA-4) as an alternative mechanism to severe disease pathogenesis." (PMID 37033961, 2023). "In addition, Tim-3+ NKT cells in COVID-19 presented a stronger capacity to secrete IFN-γ, IL-4 and IL-10 compared with healthy individuals, they also demonstrated high expression of co-inhibitory receptors such as PD-1, CTLA-4, and LAG-3." (PMID 35250975, 2022). "Among the co-inhibitory receptors, LAG3, CTLA4, and HAVCR2 were enriched in CD8+ T cells from COVID-19 patients that eventually succumbed to the disease, but PDCD1 and TIGIT were enriched in CD8+ T cells from COVID-19 patients that eventually recovered and discharged." (PMID 36119105, 2022). "Similarly, another study demonstrated that, in critical COVID-19 patients, the frequency, the proliferation as well as the protein abundance of FOXP3, CTLA-4, GITR and ICOS of CD25+ CD127− FOXP3+ Tregs enhanced, along with their increasing suppressive function." (PMID 35874688, 2022). "Of note, expression of HLA-DR and CTLA-4 negatively correlated with MAIT cell frequency in COVID-19 patients, indicating that the lower frequency of MAIT cells in peripheral blood of COVID-19 patients may result from activation-induced cell death in vivo." (PMID 33546489, 2021). "Other Food and Drug Administration-approved antiinflammatory drugs tested in models of SEB TSS may also be effective, including CTLA4-Ig which can inhibit CD28 costimulation, and the mammalian target of rapamycin (mTOR) inhibitor rapamycin, which is already in use for COVID-19." (PMID 32989130, 2020). "MAIT cells showed higher expression of CTLA4 and PD1 in severe COVID-19 but not significantly, and in convalescent patients with severe and mild symptoms CTLA expression decreased deeply." (PMID 35159352, 2022). "Interestingly, expression of exhaustion markers, such as CTLA-4 and PD-1, by MAIT cells was elevated in patients with severe COVID-19, although not significantly." (PMID 33546489, 2021).
Sepsis (71 papers, 2010 to 2026). Sepsis is defined as life-threatening organ dysfunction caused by a dysregulated host response to infection. "Cardiac-specific biomarkers previously validated in sepsis research now inform novel targeting strategies, including programmed cell death protein 1 (PD-1) and cytotoxic T-lymphocyte-associated protein 4 (CTLA-4) checkpoint inhibition." (PMID 41256846, 2025). "Mouse experiments have shown that in the sepsis model characterized by chronic alcohol intake, the increase in CTLA-4 expression is associated with poorer clinical outcomes." (PMID 41209006, 2025). "Preclinical studies have shown that blocking PD-1 or CTLA-4 can improve survival in animal models of sepsis by enhancing T-cell responses and reducing susceptibility to secondary infections." (PMID 40563999, 2025). "Another sepsis-upregulated gene Ctla4 encodes CTLA4, the immune checkpoint that mediates immunosuppression." (PMID 41229427, 2025). "The other “top genes” induced by sepsis in the spleen encode Semaphorin 3e (Sema3e), Interleukin-17F (Il17f), and Cytotoxic T lymphocyte antigen 4 (Ctla4)." (PMID 41229427, 2025). "In summary, the poor outcome of sepsis is associated with the physiological imbalance of T cells, and CTLA4 plays an important role in this and is a potential regulatory target." (PMID 39104632, 2024). "In our study, SAI was associated with a higher 28-day morality rate for patients with sepsis, and CTLA-4 MFI on CD4+ T lymphocytes was an independent risk factor for the incidence of SAI." (PMID 39104530, 2024). "CTLA-4 expression has also been shown to increase on Treg during sepsis, and this is associated with increased Treg suppressive capacity and impaired ability to clear infections such as Salmonella." (PMID 38226924, 2024). "CTLA-4 genetic variants can be an important predictor of survival in sepsis patients, and precise anti-CTLA-4 therapy can be stratified according to CTLA-4 gene variants." (PMID 38114466, 2023). "Recent studies have also explored the correlation between single nucleotide polymorphisms (SNP) within the CTLA-4 gene and sepsis severity in humans." (PMID 33613563, 2020). "A recent study by our working group revealed that the rs231775 single nucleotide polymorphism (SNP) in the CTLA-4 gene was associated with the survival of patients with sepsis and served as an independent prognostic variable." (PMID 30634576, 2019). "This most common CTLA-4 haplotype consists of the rs733618 T, rs231775 A, and rs3087243 A alleles, of which the second two are associated with unfavorable sepsis outcomes." (PMID 30634576, 2019). "To further investigate the impact of CTLA-4 genetic variants on sepsis survival, we examined the effect of two functional SNPs, CTLA-4 rs733618 and CTLA-4 rs3087243, and inferred haplotypes, on the survival of 644 prospectively enrolled septic patients." (PMID 30634576, 2019). "In conclusion, our findings underscore the significance of CTLA-4 genetic variants as predictors of survival of patients with sepsis." (PMID 30634576, 2019). "In other words, the GG genotype most likely has a reduced inhibitory function of CTLA-4, resulting in a less pronounced sepsis-associated immunosuppression and thus an enhanced clinical course, especially in the late phase of sepsis." (PMID 30310101, 2018). "The present study aimed to assess a potential association between the CTLA-4 rs231775 SNP and the survival of Caucasian patients with sepsis." (PMID 30310101, 2018). "Similarly, high CTLA-4 expression in sepsis is associated with immunosuppression, making it another biomarker for this condition." (PMID 40364841, 2025). "Collectively, current evidence indicates that TIM-3 primarily functions through Tregs to limit excessive inflammation during sepsis, whereas CTLA-4, LAG-3, and TIGIT are more strongly associated with the immunosuppressive state that emerges in the later stages of the disease." (PMID 40806563, 2025).
Sepsis (continued). "In summary, we may have found a contribution of the mTOR-autophagy-CTLA4 axis in sepsis-associated CD4+ T cell deficiency and dysfunction." (PMID 39104632, 2024). "Therefore, we proceeded to understand the role of CTLA4 in driving lymphocyte dysfunction during sepsis and the associated regulatory mechanisms." (PMID 39104632, 2024). "Numerous studies have confirmed that CTLA4 is closely associated with progression and prognosis in sepsis, but the pattern of expression, exact function, and the associated regulatory network remain unclear." (PMID 39104632, 2024). "Additionally, our finding that CTLA-4–deficient Treg can induce activation of Tconv cells both reinforces existing literature as well as documents this phenomenon in a murine model of sepsis plus chronic alcohol exposure." (PMID 38226924, 2024). "Furthermore, the co-expression of TIM-3 and CTLA-4 has been associated with suboptimal T cell function and worse clinical outcomes in sepsis patients." (PMID 38576606, 2024). "Collectively, these data show that the CTLA-4 coinhibitory pathway is implicated in sepsis immunopathology and suggest that manipulation of this pathway using mAb therapies may translate to improved outcomes for septic patients." (PMID 38226924, 2024). "First, although the correlation between CTLA-4 expression on CD4+ lymphocytes and immunosuppression, and the association between CTLA-4 expression and autophagic–lysosomal disorders, were identified among a large sample of patients with sepsis, this study was purely a clinical study." (PMID 39104530, 2024). "This study aimed to investigate the impact of these two functional single nucleotide polymorphisms (SNPs) and inferred haplotypes compound of rs733618, rs231775, and rs3087243 on the 90-day mortality of septic patients in order to further reveal the role of CTLA-4 genetic variants in sepsis." (PMID 30634576, 2019). "However, the molecular mechanisms by which CTLA-4 polymorphisms and haplotypes influence the sepsis disease severity and mortality risk remain to be identified." (PMID 30634576, 2019). "In this context, our study provides further evidence implicating CTLA-4 polymorphisms and haplotypes in determining sepsis severity and mortality, and thus they may serve as prognostic variables." (PMID 30634576, 2019). "The main finding was that in addition to our previous identification of the CTLA-4 rs231775 SNP as a prognostic variable for the outcome of septic patients, the functional CTLA-4 rs3087243 SNP and the inferred CTLA-4 haplotype H1: TAA were significantly associated with sepsis survival." (PMID 30634576, 2019). "Our findings may help identify patients at risk in clinical settings and emphasize the need for further research to reveal potential functional associations between CTLA-4 and the immune pathophysiology of sepsis." (PMID 30310101, 2018). "Our study aimed to investigate whether mortality among patients with sepsis was associated with the CTLA-4 rs231775 polymorphism." (PMID 30310101, 2018). "Moreover, the analysis of cell surface markers demonstrated that AZM reduces the immunosuppressive state following sepsis through a downregulation of coinhibitory molecules [namely cytotoxic-T lymphocyte-associated antigen 4 (CTLA-4) and programmed death 1 (PD-1)]." (PMID 33796090, 2021). "Furthermore, our study revealed that CTLA-4 rs3087243 G allele carriers showed significantly better sepsis disease severity in terms of a lower average SOFA-CNS score and a reduced need for organ support, as represented by a reduced number of ventilation days as a fraction of observation days." (PMID 30634576, 2019). "We can assume that lower expression levels of the coinhibitory regulatory CTLA-4 protein in rs3087243 G allele carriers result in an enhanced T lymphocyte host immune response, which may be beneficial in the immunosuppressive phase of sepsis." (PMID 30634576, 2019).